IRAK1 (interleukin 1 receptor associated kinase 1)
Description:
Serine/threonine-protein kinase that plays a critical role in initiating innate immune response against foreign pathogens. Involved in Toll-like receptor (TLR) and IL-1R signaling pathways. Is rapidly recruited by MYD88 to the receptor-signaling complex upon TLR activation. Association with MYD88 leads to IRAK1 phosphorylation by IRAK4 and subsequent autophosphorylation and kinase activation. Phosphorylates E3 ubiquitin ligases Pellino proteins (PELI1, PELI2 and PELI3) to promote pellino-mediated polyubiquitination of IRAK1. Then, the ubiquitin-binding domain of IKBKG/NEMO binds to polyubiquitinated IRAK1 bringing together the IRAK1-MAP3K7/TAK1-TRAF6 complex and the NEMO-IKKA-IKKB complex. In turn, MAP3K7/TAK1 activates IKKs (CHUK/IKKA and IKBKB/IKKB) leading to NF-kappa-B nuclear translocation and activation. Alternatively, phosphorylates TIRAP to promote its ubiquitination and subsequent degradation. Phosphorylates the interferon regulatory factor 7 (IRF7) to induce its activation and translocation to the nucleus, resulting in transcriptional activation of type I IFN genes, which drive the cell in an antiviral state. When sumoylated, translocates to the nucleus and phosphorylates STAT3.
Synonyms: IRAK; pelle
Tractability: Small molecule: a structure with a bound ligand is known; a high-quality ligand is known; it belongs to a druggable protein family. Antibody: its Gene Ontology location is reachable by antibodies, with high confidence. PROTAC: it is named in the literature on targeted protein degradation; UniProt records ubiquitination sites on it; ubiquitination databases record sites on it; its protein half-life has been measured; a small molecule that binds it is known.
Target class: Kinase; TKL protein kinase IRAK family; TKL protein kinase group; Enzyme; Protein Kinase
Chemical probes: IRAK4-IN-28 (high quality), JH-X-119-01 (high quality)
Gene: Protein-coding gene on chromosome X (154,010,504 to 154,019,927, reverse strand). Ensembl gene ENSG00000184216.
Subcellular location: Cytoplasm; Nucleus; Lipid droplet
Subcellular location (Human Protein Atlas): Cytosol; Nucleoplasm
Pathways (Reactome):
Immune System: IRAK1 recruits IKK complex; IRAK1 recruits IKK complex upon TLR7/8 or 9 stimulation; Interleukin-1 signaling; JNK (c-Jun kinases) phosphorylation and activation mediated by activated human TAK1; MyD88 cascade initiated on plasma membrane; MyD88 dependent cascade initiated on endosome; MyD88:MAL(TIRAP) cascade initiated on plasma membrane; NOD1/2 Signaling Pathway; TAK1-dependent IKK and NF-kappa-B activation; TRAF6 mediated IRF7 activation in TLR7/8 or 9 signaling; TRAF6 mediated induction of NFkB and MAP kinases upon TLR7/8 or 9 activation; activated TAK1 mediates p38 MAPK activation
Signal Transduction: NF-kB is activated and signals survival; PI5P, PP2A and IER3 Regulate PI3K/AKT Signaling; PIP3 activates AKT signaling; p75NTR recruits signalling complexes
Disease: SARS-CoV-2 activates/modulates innate and adaptive immune responses
Gene Ontology:
Molecular function: identical protein binding; kinase activity; protein binding; protein heterodimerization activity; protein homodimerization activity; protein kinase activity; protein kinase binding; protein serine/threonine kinase activity; signaling adaptor activity; ATP binding; heat shock protein binding; protein serine kinase activity
Biological process: canonical NF-kappaB signal transduction; interleukin-1-mediated signaling pathway; interleukin-33-mediated signaling pathway; lipopolysaccharide-mediated signaling pathway; negative regulation of canonical NF-kappaB signal transduction; positive regulation of canonical NF-kappaB signal transduction; positive regulation of leukocyte adhesion to vascular endothelial cell; positive regulation of type I interferon production; protein autophosphorylation; regulation of cytokine-mediated signaling pathway; response to interleukin-1; response to lipopolysaccharide; toll-like receptor 2 signaling pathway; toll-like receptor 9 signaling pathway; type I interferon-mediated signaling pathway; innate immune response; intracellular signal transduction; MyD88-dependent toll-like receptor signaling pathway; NLRP3 inflammasome complex assembly; regulation of MAP kinase activity; Toll signaling pathway; toll-like receptor 4 signaling pathway; toll-like receptor signaling pathway; cellular response to heat; cellular response to hypoxia; and 6 more
Cellular component: cell surface; cytosol; nucleoplasm; protein-containing complex; cytoplasm; endosome membrane; lipid droplet; plasma membrane; serine/threonine protein kinase complex; membrane; nucleus
Homologues: Orthologues: chimpanzee IRAK1 (99% identical), macaque IRAK1 (94% identical), mouse Irak1 (81% identical), rat Irak1 (80% identical), dog IRAK1 (79% identical), pig IRAK1 (78% identical), guinea pig IRAK1 (69% identical), rabbit IRAK1 (59% identical), tropical clawed frog irak1 (41% identical), zebrafish irak1 (37% identical), Caenorhabditis elegans pik-1 (18% identical), Drosophila melanogaster pll (17% identical), and 4 more. Paralogues in human: IRAK2 (25% identical), IRAK3 (23% identical), IRAK4 (19% identical), HASPIN (12% identical).
Diseases named in the same sentence as IRAK1 in open-access papers:
IRAK1 is named in the same sentence as 233 diseases in open-access papers, as found by Europe PMC text mining. Sharing a sentence is not in itself a finding about the gene and the disease. The quoted sentences say what the papers report.
breast carcinoma (36 papers, 2008 to 2026). "Elevated IRAK1 phosphorylation levels are linked to breast cancer recurrence, highlighting the significant role of IRAK1-directed NF-κB signaling in breast cancer metastasis, resistance to chemotherapy, and tumor reappearance." (PMID 38792088, 2024). "The role of IRAK1 in the activation of survival pathways leading to therapeutic resistance has been implicated in HER2-enriched breast cancer." (PMID 39451208, 2024). "It is only recently that IRAK1 has been linked to multiple cancers, including breast cancer, lymphoma and acute myeloid leukemia." (PMID 39543721, 2024). "For instance, IRAK1 upregulation causes an increase in tumor growth and metastasis of breast cancer." (PMID 37370720, 2023). "Here we report that interleukin-1 receptor-associated kinase 1 (IRAK1) is overexpressed in a subset of breast cancers, in particular triple-negative breast cancer (TNBC), where it acts to drive aggressive growth, metastasis and acquired resistance to paclitaxel treatment." (PMID 26503059, 2015). "Their findings were supported by another study that identified miR-146a/b as negative regulators of IRAK1, leading to the suppression of NF-κB activity and reduction in the metastatic potential of breast cancer." (PMID 39451208, 2024). "They discovered that the expression of IRAK1 was downregulated following direct binding of miR-146a-5p to IRAK1’s 3’-untranslated region, leading to the suppression of migration and invasion in breast cancer cells." (PMID 39451208, 2024). "Enhanced angiogenesis and metastasis were observed following the upregulation of IRAK1 in breast cancer." (PMID 37370720, 2023). "A functional study has demonstrated high expression of IRAK1 in human tumor tissues, such as hepatocellular carcinoma and breast cancer." (PMID 35193602, 2022). "Meanwhile, downregulation of IRAK1 reduced paclitaxel resistance via facilitation of apoptotic ability in breast cancer." (PMID 35193602, 2022). "The expression of the IL-1-related genes, such as Il1B, CASP1 and IRAK1, have been identified to be significantly up-regulated in breast cancer compared with normal mammary tissue." (PMID 36230739, 2022). "Meanwhile, high expression of IL1β, IRAK1 and Caspase-1 is closely correlated with reduced overall survival and distant recurrence of breast cancer." (PMID 36230739, 2022). "Higher expression of IRAK1 in breast cancer tissues stimulates the growth, migration, and invasion of cancer cells." (PMID 36140712, 2022). "The inhibition of TLR2 or its downstream targets CD14, MyD88, and IRAK1 can inhibit the proliferation of human breast cancer (BRCA) cells." (PMID 33138076, 2020). "Breast cancer patients, with higher expression of IRAK1 both before and after NCT, had a shorter survival period." (PMID 32547883, 2020). "IRAK1 is also reported to drive breast cancer cell metastasis, and its inhibition overcomes paclitaxel-induced resistance." (PMID 27504095, 2016). "Consistent with this, Oncomine analysis of two independent breast cancer cohorts showed a significant positive correlation of IRAK1 expression with metastasis events at 5 years post surgery." (PMID 26503059, 2015). "Reverse transcriptase–PCR analysis shows that IRAK1 messenger RNA is upregulated in over 80% of breast cancer cell lines as compared with MCF10A and HMEC, with IRAK1 expression being markedly higher in basal lines compared with luminal lines." (PMID 26503059, 2015). "Among them, IL-6, IL-8 and CXCL1, previously shown to be important for breast cancer CSCs10, 11, 26, were the top three cytokines that seemed to be most abundantly detected and downregulated following IRAK1 knockdown." (PMID 26503059, 2015).
breast carcinoma (continued). "Given a strong role of IRAK1 in invasive growth and mammosphere formation, we next evaluated the clinical relevance of IRAK1 expression in relation to breast cancer progression." (PMID 26503059, 2015). "We found that IRAK1 is overexpressed in a subset of breast cancers, mainly in TNBC, and pharmacologic inhibition of IRAK1 abolishes aggressive growth of TNBC and metastatic progression." (PMID 26503059, 2015). "Of these, 24 are nonsynonymous changes that occur in a diverse group of genes, including IRAK1 (possibly mutated in breast tumor B421) and RPS6KB1 (possibly mutated in BT474), which were previously identified as somatic mutations in breast cancer." (PMID 18364049, 2008). "Pacritinib inhibits constitutively activated IRAK1 phosphorylation in breast cancer cells." (PMID 38792088, 2024). "Additionally, miR-146a-5p directly targeted the 3′-untranslated IRAK1 region, leading to its downregulation in breast cancer cells." (PMID 38792088, 2024). "Additionally, IRAK1 is also involved in a functional regulatory circuit with products of chromosome 1q21.3 amplification, enriched in breast cancer, leading to breast cancer recurrence." (PMID 39451208, 2024). "IRAK1 plays a vital role in oncogenesis and tumor progression in multiple cancers and is shown to contribute to the progression of various cancers, including hepatocellular carcinoma, breast cancer, endometrial cancer, non-small cell lung cancer and melanoma." (PMID 35669566, 2022). "IRAK1 expression is increased in breast cancer paclitaxel-resistant cell lines, an IRAK1 inhibitor reverses paclitaxel resistance in triple-negative breast cancer, and IRAK1 is also a potential therapeutic target for paclitaxel resistance in nasopharyngeal carcinoma." (PMID 36091017, 2022). "Moreover, a recent study showed over-expression of IRAK1 in breast cancer and demonstrated its potential target for triple-negative breast cancer (TNBC) metastasis to overcome paclitaxel resistance." (PMID 27619757, 2016). "In terms of the relevance of IL-1β to breast cancer cell aggressiveness, breast cancer metastasis suppressor 1 has been shown to up-regulate miR-146, which targets key IL-1 receptor signaling molecules, including IRAK1 and TRAF6, and suppresses the metastasis of breast cancer cells." (PMID 27609180, 2016). "A recent research of breast cancers showed that over-expression of IRAK1 could promote TNBC growth through regulating NF-kB-related cytokines secretion." (PMID 27619757, 2016). "The results revealed that high IRAK1 expression positively correlated with reduced overall survival, distant metastasis-free survival and relapse-free survival ((P=0.0047, P=0.017 and P=2.1 × 106, respectively), suggesting a prognostic value of IRAK1 in breast cancers." (PMID 26503059, 2015). "Also in breast cancer, miR-146a and miR-146b expression suppressed IRAK1 and TRAF6, which was reported to impair NF-κB activity, resulting in reduced invasion and migration." (PMID 23335942, 2012). "Because overexpression of miR-146a/b in human MDA-MB-231 breast cancer cells, reduced thelevels of secreted IL-6 and IL-8 andsince IRAK1 is a key mediator of the expression of IL-6 and IL-8, we comparedthe basal levels of secreted IL6 and IL8 in control and miR-146a/boverexpressing HCA2 cells." (PMID 20148189, 2009). "In addition, diazoxide, a potassium channel opener, inhibits dual specificity tyrosine-phosphorylation-regulated kinase 1A (DYRK1A), an interleukin-1 receptor-associated kinase 1 (IRAK1), and threonine and tyrosine kinase (TTK) expression in breast cancer cell lines." (PMID 37370809, 2023). "A separate study on breast cancer also demonstrated that the inhibition of IRAK1 led to a reduction in MMP-2 and MMP-9 protein expression, further supporting the role of IRAK1 in the promotion of cancer cell metastasis." (PMID 39451208, 2024).
breast carcinoma (continued). "We further evaluated the total protein levels of IRAK1 from the CPTAC dataset; the results revealed higher expressions in the primary tumor of LUAD, clear cell RCC, UCEC, and breast cancer than in normal tissues." (PMID 35669566, 2022). "(ii) IRAK1 and PIN1 enzymatic activities are required for R-RT in cancer cell lines derived from multiple tumor types including HNSCC, breast cancer, colorectal cancer, and glioblastoma." (PMID 31799178, 2019). "Pacritinib inhibited constitutively activated IRAK1 phosphorylation in AML cells and in breast cancer cells with duplication of 1q23.1." (PMID 30279971, 2018). "Overexpression of miR-146a/b results in downregulation of IRAK1 and TRAF6 and subsequently inhibits NF-κB activation, leading to tumor suppression in breast cancer cells." (PMID 26697527, 2015). "miR-146a and miR-146b are highly expressed in the metastatic human breast cancer cell line MDA-MB-231 and negatively regulate NF-κB activity by targeting the 3’ UTRs of IRAK1 and TRAF6." (PMID 25598707, 2014). "The results showed that five lncRNAs including HOTAIR, DANCR, PVT1, LINC00511, and NEAT1 and 16 miRNAs and five of their targets—VEGFA, BTG2, E2F3, IRAK1, and SMAD4—have significantly different expression patterns in normal individuals compared to those with breast cancer." (PMID 36726376, 2023). "Similarly, evidence suggests that IRAK1 plays a critical role in multiple solid tumor and hematologic malignancies, most notably in AML and breast cancer, indications with high unmet need." (PMID 30279971, 2018). "IRAK1 is also related to the formation and development of series of myeloid malignancies or tumors, especially in myelodysplastic syndrome (MDS), acute myeloid leukaemia (AML), melanoma, Lung Cancer and Breast cancer." (PMID 27619757, 2016). "Mechanistically, SLC12A8 activated the TLR signaling pathway (upregulating TLR2, MyD88, IRAK1, TAK1 in CD8+ T cells), leading to increased PD-1 expression on CD8+ T cells, resulting in their functional exhaustion and enhanced invasive ability of Luminal B breast cancer cells." (PMID 41795804, 2026). "Therefore, the specific regulation of IRAK1 may be a new approach for treating various inflammatory conditions, particularly for diseases such as AML and breast cancer, which have limited effective treatment options." (PMID 38792088, 2024). "In addition, consistently up or down-regulated HSP90 client transcripts following treatment were identified shared by some of the cell lines analyzed (AHSA1, CCNB1, IRAK1), that could represent important HSP90 clients in breast cancer." (PMID 20920318, 2010). "Therefore, we speculate that inhibiting downstream targets of IL-1 (IRAK1, TRAF6, IKK) has effects on reducing osteoclastic bone resorption, while IL1β inhibition not only reduces osteoclastic bone resorption but also blocks breast cancer metastasis to bone." (PMID 36230739, 2022). "Kinases BUB1, CHEK1, IRAK1, TTK, RYK, and VRK2, identified in this study, for example, have been reported to be highly overexpressed in ER-negative breast tumors and were critical for the growth of either ER-negative only or both ER-positive and -negative breast cancer cells." (PMID 22309939, 2012).